DNM3OS (DNM3 opposite strand/antisense RNA)
Synonyms: MIR199A2HG; formerly DNM3-AS1
Gene: Long non-coding RNA gene on chromosome 1 (172,138,397 to 172,144,840, reverse strand). Ensembl gene ENSG00000230630.
Gene Ontology:
Biological process: miRNA-mediated post-transcriptional gene silencing
Cellular component: RISC complex
Diseases named in the same sentence as DNM3OS in open-access papers:
DNM3OS is named in the same sentence as 28 diseases in open-access papers, as found by Europe PMC text mining. Sharing a sentence is not in itself a finding about the gene and the disease. The quoted sentences say what the papers report.
ovarian carcinoma (10 papers, 2017 to 2023). A malignant neoplasm originating from the surface ovarian epithelium. "DNM3OS expression is significantly increased in ovarian cancer tissue and cell lines, and the increase is associated with a poor prognosis, as it enhances the proliferation, migration, and invasion ability of ovarian cancer cells." (PMID 38152068, 2023). "Collectively, the results indicate that DNM3OS expression modulates ovarian cancer EMT by regulating the expression of several EMT-linked genes and their associated pathways." (PMID 29150601, 2017). "Our experimental data showed alterations in DNM3OS expression were linked to EMT in ovarian cancer through changes in cell migration and invasion and EMT-linked RNA and protein levels, and ovarian cancer patient survival." (PMID 29150601, 2017). "DNM3OS regulates gene expression post-transcriptionally, and overexpression of DNM3OS has been shown to be associated with tumor progression and radio resistance in ovarian cancer, gastric cancer, and esophageal squamous cell carcinoma." (PMID 34218261, 2021). "We showed that knockdown of DNM3OS reduces EMT-linked proteins and inhibited ovarian cancer cell migration and invasion, suggesting that miR-214 and DNM3OS may both contribute to EMT." (PMID 29150601, 2017). "For ovarian cancer patients treated with platin, five lncRNAs including LINC01134, HAR1A, LINC01139, LINC-PINT, and DNM3OS were significantly associated with PFS." (PMID 32260415, 2020). "To further elucidate the contribution of DNM3OS in EMT in ovarian cancer and to experimentally validate our bioinformatics data, we evaluated knockdown of DNM3OS in ovarian cancer cells through multiple approaches." (PMID 29150601, 2017). "Our results together with previously published data indicate TWIST1 regulates the expression of DNM3OS in ovarian cancer cells." (PMID 29150601, 2017). "We observed that knockdown of TWIST1 resulted in significantly reduced levels of DNM3OS in SKOV3 ovarian cancer cells (two-tailed t-test P < 0.008)." (PMID 29150601, 2017). "DNM3OS was overexpressed in ovarian cancer and facilitated ovarian cancer progression, and its high expression might lead to a poor prognosis; the conclusion is similar to our research." (PMID 37064863, 2023). "It was proved that the overexpression of DNM3OS played a role in the development of ovarian cancer." (PMID 36011053, 2022). "Therefore, DNM3OS regulates ovarian cancer cell movement, which is a critical contributor to metastasis." (PMID 29150601, 2017). "Therefore, our results elucidate lncRNA that regulate EMT and demonstrate DNM3OS specifically contributes to EMT in ovarian cancer." (PMID 29150601, 2017). "Furthermore, increased expression of DNM3OS significantly correlated with reduced overall survival for patients with ovarian cancer." (PMID 29150601, 2017). "Therefore, overall, our results indicate lncRNA participate in ovarian cancer cell EMT, and specifically, increased DNM3OS expression by amplification or by TWIST1 overexpression contributes to EMT in ovarian cancer." (PMID 29150601, 2017). "A previous study has reported that the Dnm3os locus is regulated by TWIST1, which promotes cancer stemness, inflammation, and proliferation of human ovarian cancer cells." (PMID 32019274, 2020). "Expression data also indicate a significant positive correlation between DNM3OS and TWIST1 expression in ovarian cancer." (PMID 29150601, 2017). "Taken together, our comprehensive analysis provides essential insights into ovarian cancer EMT and reveal the critical lncRNA and specifically, DNM3OS that regulate it." (PMID 29150601, 2017). "Reannotation of microarray probe sets showed that DIO3OS, DNM3OS, MIAT, and MEG3 lncRNA were detected in the two ovarian cancer subtypes at levels similar to known protein coding EMT-linked genes." (PMID 29150601, 2017).
ovarian carcinoma (continued). "To determine the functional significance of altered DNM3OS levels in ovarian cancer cell EMT, we evaluated the effects on RNA and protein of knocking down DNM3OS in ovarian cancer cells." (PMID 29150601, 2017). "Cellular fractionation revealed DNM3OS is localized to the nucleus and not to the cytoplasm of ovarian cancer cells." (PMID 29150601, 2017). "DNM3OS has been reported to be a transcriptional target of TWIST1, which regulates ovarian cancer EMT40,41, and was overexpressed in the mesenchymal subtype of ovarian cancer." (PMID 29150601, 2017). "To gain additional insight into DNM3OS regulation of EMT genes and determine whether DNM3OS has the potential to regulate the expression of EMT genes, we evaluated where DNM3OS resided in ovarian cancer cells." (PMID 29150601, 2017).
diabetes (4 papers, 2021 to 2024). "Dnm3os, or dynamin 3 opposite strand, is another lncRNA associated with inflammation responses that promote diabetes and accelerate atherosclerosis." (PMID 38774880, 2024). "In diabetic conditions, the expression levels of nucleolar proteins decrease, leading to an increase in Dnm3os and promoting the expression of inflammatory genes, indicating Dnm3os plays a role in diabetes and accelerated atherosclerosis." (PMID 38774880, 2024). "In addition, DNM3OS has been shown to promote the inflammatory response of macrophages in diabetes via an independent mechanism." (PMID 38152068, 2023). "Conversely, Dnm3os knockdown with siRNAs in macrophages from diabetic db/db mice ameliorated the enhanced expression of inflammatory genes (Il6, Tnf, Itgax, and Nfkbiz) and phagocytosis of E.coli bioparticles, clearly supporting its role in diabetes-induced inflammation." (PMID 34234740, 2021). "Moreover, GapmeR-mediated knockdown of human DNM3OS in human THP1 monocytes inhibited inflammatory genes (IL6, TNF, and ITGAX) and phagocytosis similar to actions of the mouse ortholog, suggesting DNM3OS upregulation in humans likely contributes to enhanced inflammation in diabetes." (PMID 34234740, 2021). "However, Dnm3os levels have not been examined in endothelial cells (ECs) and VSMCs in diabetes." (PMID 34234740, 2021).
esophageal squamous cell carcinoma (4 papers, 2020 to 2021). Esophageal squamous cell carcinoma (ESCC) is a type of esophageal carcinoma (EC) that can affect any part of the esophagus, but is usually located in the upper or middle third. "Furthermore, dysregulated DNM3OS is implicated in several cancers, including gastric cancer, ovarian cancer, and esophageal squamous cell carcinoma." (PMID 32947897, 2020). "For example, FOXO1 activates DNM3OS in esophageal squamous cell carcinoma." (PMID 34834139, 2021). "Two lncRNAs, POU6F2-AS2 and DNM3OS, were involved in DSB repair in esophageal squamous cell carcinoma (ESCC)." (PMID 32585857, 2020).
atherosclerosis (3 papers, 2021 to 2024). A disease characterized by the build-up of fatty material and calcium deposition in the arterial wall resulting in partial or complete occlusion of the arterial lumen. "This suggest that Dnm3os play a role in DM and accelerated atherosclerosis." (PMID 37226245, 2023). "A similar regulation of Dnm3os was observed in macrophages from high-fat diet-induced insulin-resistant mice, streptozotocin (STZ)-induced type 1 diabetic mice, and STZ-induced diabetic apolipoprotein E deficient mice (a model of accelerated atherosclerosis) compared with controls." (PMID 37226245, 2023). "Dnm3os is significantly upregulated in CD14+ monocytes of diabetic patients and observed in various diabetic and atherosclerosis-accelerated mouse models." (PMID 38774880, 2024).
gastric cancer (2 papers, 2020 to 2021). A primary or metastatic malignant neoplasm involving the stomach. "Studies have observed that the expression of DNM3OS is upregulated in gastric cancer tissues and cell lines." (PMID 33490103, 2020).
alveolar soft part sarcoma (1 paper, 2020). An alveolar soft part sarcoma occurring in adults. "Increased Dnm3os expression was also observed both in human and mouse synovial sarcomas compared with Ewing sarcoma, alveolar soft part sarcoma, or rhabdomyosarcoma, suggesting the importance of the locus in synovial sarcoma development." (PMID 32019274, 2020).
cervical cancer (1 paper, 2021). A primary or metastatic malignant neoplasm involving the cervix. "Deletion of the region mediating the interaction between SPINT1-AS1 and DNM3OS, overexpression of miR-214, and inhibition of Wnt/β-catenin signaling all reversed the roles of SPINT1-AS1 in cervical cancer." (PMID 34350182, 2021). "The 5′ 70 nucleotides of SPINT1-AS1, which mediates the interaction between SPINT1-AS1 and DNM3OS, are also responsible for the downregulation of miR-214 level, the upregulation of β-catenin, Wnt/β-catenin signaling activation, and the oncogenic roles of SPINT1-AS1 in cervical cancer." (PMID 34350182, 2021).
esophageal cancer (1 paper, 2020). A primary or metastatic malignant neoplasm involving the esophagus. "As the tumor promoting effect of Dnm3os via cancer-associated fibroblasts was also demonstrated in esophageal cancer, dynamic modulation of the tumor microenvironment might also be achieved by the Dnm3os/miR-214 axis." (PMID 32019274, 2020).
gastrointestinal stromal tumours (1 paper, 2022). "In addition, studies have reported that DNM3OS is associated with poor prognosis of gastrointestinal stromal tumours and liver cancer." (PMID 35031063, 2022).
heart failure (1 paper, 2023). Inability of the heart to pump blood at an adequate rate to meet tissue metabolic requirements. "Given that Dnm3os has been extensively studied in diseases such as pulmonary fibrosis and heart failure, we conducted an in-depth study for Gm29233, due to its unreported role." (PMID 36787190, 2023).
ischemia (1 paper, 2021). A hypoperfusion of the BLOOD through an organ or tissue caused by a PATHOLOGIC CONSTRICTION or obstruction of its BLOOD VESSELS, or an absence of BLOOD CIRCULATION. "To validate the function of GM18840, Meg3, Dnm3os, and Pvt1 in MIRI, we carried out RNA-seq analysis in an in vitro model of simulated ischemia." (PMID 34322480, 2021).
liposarcoma (1 paper, 2020). A usually painless malignant tumor that arises from adipose tissue. "Increased expression of DNM3OS and miR-214 was associated with worse prognosis in dedifferentiated liposarcoma, indicating common functions for miR-214 in immature and aggressive phenotypes of soft part sarcomas." (PMID 32019274, 2020).
male infertility (1 paper, 2023). The inability of the male to effect fertilization of an ovum after a specified period of unprotected intercourse. "DNM3OS was found to regulate the apoptosis and senescence of spermatogonia by providing miR-214-5p and decreasing E2F2 expression, suggesting it as a novel target for gene therapy of male infertility." (PMID 38152068, 2023).
microcephaly (1 paper, 2024). A congenital or acquired developmental disorder in which the circumference of the head is smaller than normal for the person's age and sex. "Patients with small deletions of this chromosomal region, affecting DNM3OS and the incumbent miRNAs, have skeletal abnormalities including short stature, microcephaly and brachydactyly, and, in mouse, are somewhat phenocopied by deletion of Dnm3os and, therefore, the miR199a∼214 cluster." (PMID 39314058, 2024).
neuroblastoma (1 paper, 2017). Neuroblastoma (NB) is the most common solid, extracranial childhood tumor. "Moreover, overexpression of TWIST1 in neuroblastoma cells resulted in increased DNM3OS levels, and luciferase reporter assays showed that the TWIST1-binding domain in the promoter of the DNM3OS locus was necessary for expression." (PMID 29150601, 2017).
osteoarthritis (1 paper, 2023). A noninflammatory degenerative joint disease occurring chiefly in older persons, characterized by degeneration of the articular cartilage, hypertrophy of bone at the margins and changes in the synovial membrane. "DNM3OS expression is downregulated in patients with osteoarthritis, and its overexpression was found to inhibit the apoptosis of CHON-001 chondrocytes." (PMID 38152068, 2023).
retinoblastoma (1 paper, 2018). A malignant tumor that originates in the nuclear layer of the retina. "The results of microarray analysis showed that lncRNAs HOTAIR, CCAT1, DNM3OS, HIF1A‐AS1, MEG3 and 7SK expressions were up‐regulated, and lncRNAs PCAT1, MIR31HG, BCAR4, RRP1B and H19 were down‐regulated within retinoblastoma tissues." (PMID 30030888, 2018).
serous ovarian cancer (1 paper, 2020). "For serous ovarian cancer patients treated with platin, five lncRNAs including HAR1A, LINC00886, LINC01139, LINC-PINT, DNM3OS were significantly associated with PFS." (PMID 32260415, 2020).
synovial sarcoma (1 paper, 2020). "The fusions induce upregulation of both DNM3OS and miR-214, as seen in the murine synovial sarcoma with retroviral integration at the Dnm3os locus." (PMID 32019274, 2020). "Nevertheless, exogenous introduction of miR-214 or Dnm3os into synovial sarcomas and silencing of miR-214 by anti-miR-214 did not induce growth promotion, migration, or invasion, suggesting that miR-214 might not function in a cell intrinsic manner." (PMID 32019274, 2020).
cancer (8 papers, 2013 to 2023). A tumor composed of atypical neoplastic, often pleomorphic cells that invade other tissues. "We evaluated the correlations between the mRL expression level and the six immune subtypes and found that all of them were related to pan-cancer immune subtypes and elevated C1, C2 and C6 subtypes with upregulated expression of DNM3OS." (PMID 36011053, 2022). "Further, an upregulated expression of DNM3OS in KYSE-30 (~39.20-fold) and KYSE-140 (~38.30-fold) observed in condition-media containing cancer-associated fibroblasts (CAFs) compared to the cells cultured in the standard medium." (PMID 32947897, 2020). "At the same time, the role of DNM3OS in other malignant tumors has been confirmed." (PMID 37064863, 2023). "DNM3OS was highly enriched in the calcium signaling pathway, the focal adhesion pathway, the hematopoietic cell lineage pathway, the neuroactive ligand–receptor interaction pathway and cancer pathways." (PMID 36011053, 2022). "DNM3OS has been revealed as a potential tumor promoter in some human cancers." (PMID 31992960, 2020). "In normal development, malignant tumors, and various noncancerous diseases, DNM3OS functions at the junction of key pathways that regulate important molecular pathways and cellular processes." (PMID 38152068, 2023). "The expression pattern of lncRNAs in 33 cancers and the heatmap showed inter-tumor heterogeneity, but in most cancers, the expression level of WAC-AS1 was higher in tumor tissues, whereas the expression level of DNM3OS was the opposite, which was consistent with the expression trend in OV." (PMID 36011053, 2022). "The expression pattern of the four mRLs in pan-cancer showed intertumor heterogeneity, but in most cancer types, WAC-AS1 had a higher expression in tumor tissues, whereas the expression level of DNM3OS was the opposite, which was consistent with the expression trend in OV." (PMID 36011053, 2022).
tumor (8 papers, 2018 to 2022). "The results indicated that DNM3OS expression was positively associated with tumor size, mitotic count, NIH risk classification, and mutational status." (PMID 34218261, 2021). "An analysis of 251 patients with GISTs showed that high DNM3OS expression was associated with tumor size, mitotic count, NIH risk classification, PFS, and OS of patients with GISTs." (PMID 34218261, 2021). "DNM3OS expression was also higher in tumor tissues than in normal tissues and was associated with tumor stage." (PMID 33050576, 2020). "Taken together, these lines of evidence suggest that the upregulation of DNM3OS mediated by chromosomal rearrangement could lead to the proliferation of tumor cells and contribute to DDLPS progression." (PMID 31831742, 2019).
DNM3OS also shares sentences with these, for which no sentence is quoted: Ewing sarcoma (1 paper); Huntington disease (1); liver cancer (1); liver fibrosis (1); pulmonary fibrosis (1); rhabdomyosarcoma (1); soft part sarcomas (1).